LEP (leptin)
Diseases named in the same sentence as LEP in open-access papers (continued):
Sharing a sentence is not in itself a finding about the gene and the disease.
Obesity (continued). "LEP, a candidate gene of obesity mapped in chromosome 7q31.3, comprises three exons spanning approximately 20 kb and encodes a 16‐kDa protein, leptin." (PMID 31914480, 2020). "Second, we used mice with DM that was induced by using repeated low-dose STZ injections to avoid the contribution of an effect related to obesity or leptin abnormality on immune function." (PMID 32993618, 2020). "Recently, leptin has been found to play a role in obesity-related hypertension as has adiponectin in adult men." (PMID 32085704, 2020). "Similar to our outbred genetically normal nonobese T2D rat model, other diabetic rodent models (spontaneous, abnormal leptin/leptin receptor signaling, diet‐induced obesity) also showed a similar trend in the three‐point bending test." (PMID 33103024, 2020). "In obesity, it can directly or indirectly affect immune tolerance by altering the secretion of adipokines (mainly leptin, adiponectin, and mucin) and/or cytokines (interleukin-6, tumor necrosis factor alpha, and interleukin)." (PMID 32256575, 2020). "The Iberian pig has proven particularly valuable in obesity studies, as it is naturally leptin resistant, with exacerbated appetite and fattening." (PMID 32150837, 2020). "Taking into consideration that obesity itself can cause oxidative stress, we found that the LEPR rs8179183 GG genotype specifically affects oxidative stress markers and alters leptin and adiponectin levels." (PMID 32517169, 2020). "Among the metabolic components linking obesity and cancer, adipokines, especially adiponectin, leptin, and resistin, existing in BMF, are known to induce tumorigenesis." (PMID 33112535, 2020). "We examined the responses of glia in the dorsal vagal complex (DVC) to the adipokine leptin and high fat diet-induced obesity." (PMID 32152264, 2020). "Leptin, an adipocytokine secreted by adipocytes, has an important regulatory role in obesity and metabolism." (PMID 32316577, 2020). "In this regard, a growing body of data have outlined the role of the obesity cytokine leptin-mediated pathways in mammary tumorogenesis, proposing this adipokine as a key member of the molecular network in obesity." (PMID 32260113, 2020). "BMI and measured leptin concentration in blood were used as a proxy for maternal obesity and fat mass." (PMID 33154737, 2020). "In people with obesity, this receptor is overactive and has been shown to contribute to leptin resistance, which is when the brain becomes less receptive to leptin." (PMID 33210603, 2020). "The adipokine leptin is involved in energy homeostasis in healthy individuals, while in obesity leptin participates in the pro-inflammatory processes." (PMID 33050319, 2020). "IKKβ/NF-κB signaling then acts both upstream and downstream from ER stress and autophagy that contributes to the development of leptin resistance and obesity." (PMID 32760236, 2020). "Further studies at later developmental time-points evaluating the relationship between plasma leptin and hypothalamic LR function, following maternal HFHC-induced obesity would help clarify the role of leptin in programming obesity." (PMID 32987812, 2020). "In this sense, leptin, produced by adipocytes, is a key regulator of appetite and is present in elevated concentrations in obesity." (PMID 32630697, 2020). "While the etiology of obesity is complex, it is possible that increased leptin signaling promotes excessive inflammation and potentially cytokine storm." (PMID 33584724, 2020). "This goes along with the basic physiology of leptin and its effects on hypothalamus as an anti-obesity hormone." (PMID 33489589, 2020). "It is reported that obesity-related hormone leptin promotes FAO in ECs by increasing CPT1α activity, suggesting obesity not only provides the fuel but also is capable of triggering host cell metabolism." (PMID 33330490, 2020).
Obesity (continued). "The adipocytokines leptin and IL-6 inhibit regulatory T cells, whereas obesity alters cell-mediated Th1 immune responses, resulting in CD3 and CD4 T helper cells and CD8 T suppressor/cytotoxic cells defects." (PMID 32256575, 2020). "For instance, leptin, which is often increased in obesity while their brain is insensitive to this hormone, has an inhibitory role on olfactory function in mice." (PMID 33328935, 2020). "Intriguingly, activation of these pathways is regulated by leptin, the proinflammatory mediator released mainly by adipocytes that link the immune system with obesity-related insulin and leptin resistance." (PMID 32824322, 2020). "The complex molecular mechanisms of leptin resistance in obesity are not fully understood but seem to be selective, such as insulin resistance." (PMID 32230732, 2020). "Several studies have reported elevated leptin and insulin resistance in CRD conditions, associated with weight gain, obesity and type-2 diabetes." (PMID 32581213, 2020). "In contrast, since obesity prevalence has only increased from the data collection period to the present time, we expect a crescent impact of leptin on T production." (PMID 33179018, 2020). "Among those receptors, leptin is an important adipokine, derived from adipose tissues, and is involved in obesity, immune responses, and inflammation." (PMID 33110098, 2020). "It is known that adipose tissue in obesity secretes a high level of pro-inflammatory adipokines, such as leptin, TNFα and ILs, but few anti-inflammatory cytokines such as adipoQ." (PMID 31989870, 2020). "Disruption of leptin signaling leads to obesity-induced cardiac remodeling, and this progression of cardiac hypertrophy to heart failure is a major contributor to morbidity and mortality in obese patients." (PMID 32346034, 2020). "Despite the growing evidence linking obesity and adipokines namely leptin and its receptors with PCa, it is still a matter of debate." (PMID 32573960, 2020). "This is in accordance with other studies, which found leptin increased in children and adults with obesity and a significant pre/postintervention decrease compared with control groups." (PMID 32154197, 2020). "The classic adipokines leptin, adiponectin, and resistin have been extensively reviewed, and their role in the pathogenesis of obesity-related disorders has been concisely outlined." (PMID 32604889, 2020). "Leptin acts over hypothalamic neurons to reduce appetite and the development of obesity in aging climacteric women has been proposed to consist on a state of leptin resistance." (PMID 32555994, 2020). "Leptin crosstalks with various molecular mediators of the obesity such as VEGF, estrogen, IGF-1, insulin and inflammatory cytokines." (PMID 33511131, 2020). "In this context, pro-opiomelanocortin (POMC)-expressing neurons located into the hypothalamic arcuate nucleus (ARC) are critically involved in leptin’s effects on glucose homeostasis in obesity and insulin resistance states." (PMID 33192583, 2020). "Adiponectin and leptin are produced primarily by adipose tissue and are related to measures of obesity, such as BMI." (PMID 32397260, 2020). "Based on different reports, leptin can have other effects, such as obesity-related hypertension as well as pro-thrombotic properties, in the cardiovascular system." (PMID 33148166, 2020). "Circulating leptin levels (physiological range approximately 16 ng/mL) reflect the amount of energy stored in the adipose tissue and are correlated with the degree of obesity." (PMID 32824322, 2020). "Leptin levels are generally elevated in obesity, and obese individuals are often leptin resistant, as seen in the failure of recombinant leptin to cause weight loss." (PMID 33076921, 2020). "The purpose of this study was to expand the comprehension of the relationships among the LGG, leptin resistance, and host gut microbiota in diet-induced obesity in mice." (PMID 32846917, 2020).
Obesity (continued). "Disruption in central leptin signaling, such as leptin resistance, leads to the development of metabolic diseases, such as obesity, type 2 diabetes, and hypertension, all of which are leading causes of death in the modern world." (PMID 33114326, 2020). "Adipocyte hypertrophy has been reported to lead to insulin resistance and liver fibrosis via dysregulation of adipokines, typically evidenced by elevated levels of leptin and suppression of adiponectin production in obesity." (PMID 32163524, 2020). "Based on the concentration of leptin, history of the occurrence and the degree of overweight/obesity, the individually selected dose of cisplatin and the frequency of its administration can be predicted." (PMID 32531934, 2020). "In numerous studies, people with obesity have conducted different training programs, reporting improvements in the plasmatic levels of leptin, with significant decreases." (PMID 32854366, 2020). "This work demonstrates that obesity-altered ASCs, via enhanced secretion of leptin, promote IL-6 and NOTCH signaling pathways in ER+BCCs leading to radiation resistance." (PMID 32326381, 2020). "The upregulation of LEPR and LEP and associated SOC3 in response to SARS-CoV-2 infection was in line with mechanisms that are dysregulated in the state of obesity." (PMID 33071815, 2020). "The group with elevated leptin levels included 3930 individuals (1933 females, 1997 males) with excess body weight and obesity (25–35 kg/m2)." (PMID 32178438, 2020). "Compared with the control group, the body weight, peritesticular fat, Lee's index, total cholesterols, triglyceride, high-density lipoprotein, and leptin of obesity group rats and leptin of ZnSO4-treated group rats increased significantly." (PMID 32462040, 2020). "In experimental studies, leptin-deficient ob/ob mice, leptin receptor-deficient db/db mice, and HFD-induced obese mice are common models used for the study of obesity." (PMID 32585823, 2020). "Leptin actions in resident macrophages can also be indirectly through mast cells, a migrant cell of connective tissue that contribute to obesity and diabetes." (PMID 32839413, 2020). "The proband’s fasting leptin level was 19.0 ng/mL, which is mildly elevated for age, but appears to be below expectations for her degree of obesity." (PMID 33210059, 2020). "Since in obesity adipokine plasmatic levels changes, in this study leptin (LEP) system was evaluated in the skin of obese dogs to observe changes in peripheral tissue." (PMID 33316917, 2020). "This difference in sweet detection and consumption is thought to be related to the leptin level, which increases the threshold to sweet taste in individuals with obesity." (PMID 32635385, 2020). "Leptin was significantly higher in patients with obesity (51.24 ± 18.12 vs. 9.10 ± 2.99: p-value < 0.0001)." (PMID 33489589, 2020). "A similar insulin-resistant phenotype has also been reported in leptin-deficient ob/ob mice fed the GAN diet (GAN ob/ob-NASH mice), an obesity-prone accelerated model of NASH, which lends further support to the translatability of GAN diet-based mouse models." (PMID 32631250, 2020). "Maternal BMI (kg/m2) and serum leptin (ELISA) were used as proxy measures of obesity and maternal fat mass, respectively." (PMID 33154737, 2020). "Leptin resistance is a common characteristic of diet-induced obesity, in which anorectic responses to leptin are lower, and hyperleptinemia is a typical finding." (PMID 32565792, 2020). "Leptin is a hormone produced by the obesity gene of adipocytes (Caro, Sinha, Kolaczynski, Zhang, & Considine, 1996)." (PMID 32180965, 2020). "The hormone leptin plays an important role regarding intake of food, and the homeostasis of body weight is commonly increased in obesity, a condition known as leptin resistance." (PMID 33312720, 2020). "Leptin promotes inflammatory responses in obesity, while adiponectin inhibits TNF-α production in macrophages and is considered to have anti-inflammatory properties." (PMID 33086562, 2020).
Obesity (continued). "In conclusion, leptin is able to increase CB activity, being involved in obesity and its cardiovascular consequences." (PMID 32756352, 2020). "Many reports have revealed the potential role of adiponectin (decreased in obesity) and leptin (elevated in obesity) in allergic asthma." (PMID 32143340, 2020). "Metabolic pathways most significantly enriched by the list of candidate genes include Relaxin Signaling, Leptin Signaling in Obesity, IGF-1 Signaling, PXR/RXR Activation and HIF1α Signaling pathways." (PMID 33499953, 2020). "Most of the proteins involved in the monogenic obesity are involved in the leptin–melanocortin signaling pathway." (PMID 32982666, 2020). "The circulating levels of adiponectin are reduced in patients with obesity, whereas another adipokine leptin levels in the blood are significantly increased in obesity patients." (PMID 32015774, 2020). "The high leptin levels in obesity have immune-stimulatory effects on many immune cells, but due to leptin resistance and altered immune cell functionality, also dysregulated/suppressive immune responses occur." (PMID 32528467, 2020). "Reduced leptin signaling also leads to obesity in ob mice that lack leptin, and in animals fed a high fat diet (HFD) which causes leptin resistance." (PMID 32452759, 2020). "For example, emerging data suggest that the POMC promoter, which is critical for hypothalamic leptin signaling, is highly methylated in obesity." (PMID 32407841, 2020). "Regarding obesity related hormones our results revealed a significant reduction in leptin and rise in adiponectin levels following consumption of low diet derived AGEs." (PMID 33335235, 2020). "This proinflammatory state is a result of increased IL-6 from leptin and insulin resistance that takes place in obesity." (PMID 33202598, 2020). "Adipokines, especially leptin and adiponectin, seem to induce an early onset of puberty in girls and boys with obesity by affecting the hypothalamic‐pituitary‐gonadal (HPG) axis." (PMID 32003144, 2020). "The contribution of the leptin-TRH-BAT/lumbar SNA pathway in obesity development and maintenance, in the difficulties of obese individuals in maintaining weight loss, as well as in increased SNA and hypertension, also deserve future consideration." (PMID 32538782, 2020). "Specifically, hypothalamic inflammation in obesity is thought to contribute to impaired action of leptin, insulin, and other hormones." (PMID 32993686, 2020). "SOCS3 is also a leptin resistance inducer, thus leads to increased lipogenesis, obesity and hepatic steatosis." (PMID 32158492, 2020). "Similar to obesity, serum leptin levels have been shown to be elevated inpatients with idiopathic PAH (IPAH) and scleroderma-associated PAH independentlyof proinflammatory cytokines." (PMID 32999709, 2020). "Leptin secretion is increased in obesity; thus, the serum leptin concentration is used as an indicator of body fat mass in obesity studies (Seo, Han, Park, Koh, & Lee, 2010)." (PMID 32180965, 2020). "Studies on rat and human PBMCs reported an altered post-receptor signaling in obesity, as the leptin-induced activation of JAK/STAT signaling components were diminished in obese individuals compared to normal weight subjects." (PMID 32231659, 2020). "Leptin is decreased with calorie restriction and intermittent fasting, and is increased with obesity due to the development of leptin resistance." (PMID 31906264, 2020). "In this review, leptin actions in white adipose tissue will be summarized in the context of obesity." (PMID 32839413, 2020). "Studies suggest that obesity is the one of the most important risk factors for CAD and one of the important factors underlying the link between obesity and CAD is the leptin and adiponectin levels secreted by adipose tissue." (PMID 33148166, 2020).
Obesity (continued). "The presence of the hormone receptor in bone metastasis here reported demonstrates that metastatic cells are also responsive to leptin, suggesting that obesity can contribute to metastasis development." (PMID 33213024, 2020). "Mice that lack functional leptin or LepR (ob/ob, db/db) are hyperphagic and display severe obesity with hyperglycemia and insulin resistance." (PMID 32731387, 2020). "Like for AQP7, leptin has been shown to regulate hepatic AQP9 abundance, thus complicating the interpretation of the effect of obesity on AQP9 abundance in leptin deficient mice." (PMID 33193093, 2020). "As the blood leptin concentration increases proportionally to the degree of obesity and aging in both humans and dogs, the regulation of leptin activity is crucial for managing and inhibiting cancer." (PMID 33255835, 2020). "Leptin acts via the hypothalamus to control energy balance and feeding behavior Thus, leptin, also called an anti-obesity hormone, reduces food intake and increases energy expenditure." (PMID 32485856, 2020). "Since leptin and RSTN are implicated in the etiology of obesity and metabolic syndrome, it is important to characterize the hormonal cross talk between the peripheral and central loci at the cellular and molecular levels." (PMID 32545900, 2020). "Many adipokines, such as leptin and adiponectin, play an important role in regulating immunity and are considered to be a key link between obesity and obesity-related diseases." (PMID 32256575, 2020). "As reported, obesity is considered to be a status of chronic and low-grade inflammation which leads to the disturbed secretion of multiple cytokines, such as leptin, adiponectin, and chemokines, that play a modulatory role in inflammatory response." (PMID 33597945, 2020). "In normal individuals, insulin upregulates leptin production to increase satiety when glucose levels are high; however, obesity induces leptin resistance, resulting in high blood leptin concentrations and high food intake." (PMID 33142995, 2020). "All patients with this congenital leptin deficiency showed similar phenotypic manifestations, such as rapid weight gain in the first three months of life, resulting in early-onset obesity, hyperphagia, and significantly low serum leptin levels." (PMID 33261141, 2020). "The animal models, especially those with impaired leptin signaling, are widely used in diabetes and obesity research." (PMID 33008429, 2020). "Outcome measures were albuminuria, leptin/adiponectin ratio, obesity indicators, and glycaemic control." (PMID 32652863, 2020). "Elevated leptin level typically generates a strong signal that functions to prevent obesity, however, such effect is weak or disrupted in already-obese subjects." (PMID 32731387, 2020). "Severe insulin resistance can occur in the setting of severe obesity syndromes resulting from pathogenic variants in MC4R, POMC, LEP, and LEPR." (PMID 33210059, 2020). "Etiological and pathophysiological studies of obesity establish that leptin is a central biomolecule for the development of this pathology, although the molecular mechanisms mediated by this adipokine have not yet been fully described." (PMID 33334030, 2020). "Our data provide new insight into the mechanism of the interaction between IFNγ and leptin signaling, which furthers our understanding of the relationship between obesity and the development of Th1-mediated autoimmune diseases." (PMID 33379198, 2020). "Pathological levels of leptin induced by obesity have been identified as limiting ICI response, while leptin receptor blockade has improved ICI response." (PMID 32244756, 2020). "The genetic causes of syndromic monogenic obesity are not fully elucidated to date, while all genes that contribute to non-syndromic monogenic obesity are involved in energy homeostasis through the leptin-melanocortin pathway." (PMID 33088334, 2020).